ITK (IL2 inducible T cell kinase)
Diseases named in the same sentence as ITK in open-access papers (continued):
Sharing a sentence is not in itself a finding about the gene and the disease.
ovarian carcinoma (2 papers, 2021). A malignant neoplasm originating from the surface ovarian epithelium. "Notebably, ITK was one of the the top three genes to inhibit metastasis in the mouse model of ovarianS cancer." (PMID 34702300, 2021). "Generally, ITK plays an important role in the inflammatory processes and oncogenesis, which pave the promising way to develop inhibitors of the ovarian cancer." (PMID 34702300, 2021). "The expression of ITK was significantly lower in patients with ovarian cancer than normal samples, especially in the patients with un-regional metastasis." (PMID 34702300, 2021). "This study was to investigate the predicitive role of ITK in the prognosis of patients with ovarian cancer." (PMID 34702300, 2021). "Together, these data provide insights into the potential role of ITK, with implications for the future development of tansformative ovarian cancer therapeutics." (PMID 34702300, 2021). "In summary, we identified a strong correlation between differential ITK expression and ovarian cancer development and prognosis, which was verified by TCGA and GEO data sets analysis." (PMID 34702300, 2021). "Our data showed that ITK expression was significantly inhibited in the metastatic mouse model, which suggested its essential role in the occurrence and development of ovarian cancer metastasis." (PMID 34702300, 2021). "To further explore the prognostic role of ITK in ovarial cancer, we divided these samples into two groups (low and high-ITK group) based on the mean value as a cut off threshold." (PMID 34702300, 2021). "Integrately, ITK could predict prognosis of patients with ovarian cancer independently as a favorable biomarker." (PMID 34702300, 2021). "Next, we investigated whether the alteration of ITK expression in the ovarian cancer metastasis mouse model was consistent with that in the ovarian cancer patients." (PMID 34702300, 2021). "We filtered various significant genes (n = 6722) associated with metastasis within a large-scale functional genomic CRISPR/Cas9 knock-out library including 122,756 single guide RNAs, and identified ITK (IL2 Inducible T Cell Kinase) as a potential cancer suppressor gene for ovarian cancer metastasis." (PMID 34702300, 2021). "Integrated analysis revealed dysregulated molecular processes including predominantly oncogenic signaling pathways in low-ITK group but immune related pathways in high-ITK group, which suggested ITK might inhibit distant metastasis in ovarian cancer." (PMID 34702300, 2021). "Moreover, our enrichment analysis results highlighted the prognostic role of ITK in ovarian cancer were involved in immunology function." (PMID 34702300, 2021). "However, we predominantly focused on exploring the clinical analysis with bioinformatics methods to reveal the mechanism of ITK with low expression in the ovarian cancer patients." (PMID 34702300, 2021). "We collected 6,722 significant genes correlated with metastasis within CRISPR/Cas9 library and identified ITK as a key factor to predict clinical outcomes of patients with ovarian cancer in the Cancer Genome Atlas (TCGA) and Gene Expression Omnibus (GEO) datasets." (PMID 34702300, 2021). "All these data showed that ITK could act as a cancer suppressor gene in patients with ovarian cancer and had a similar function to CD244 and SOCS1." (PMID 34702300, 2021). "The similar results in both data sets showed that the HRs of patients with low ITK expression was more significant than those with high ITK expression, which suggested that the expression of ITK can be used as an independent prognostic factor to predict the prognosis of patients with ovarian cancer." (PMID 34702300, 2021). "Therefore, we provided a landscape of ITK in ovarian cancer from the mouse model to patients, which could help us understand the correlation between ITK expression and the prognosis of patients with ovarian cancer." (PMID 34702300, 2021).
ovarian carcinoma (continued). "Ovarian cancer has been extensively studied so far, yet the role of ITK in ovarian cancer has not been elucidated in many publications." (PMID 34702300, 2021).
parasite infection (2 papers, 2014 to 2023). "Though, ITK seems to be dispensable for general TCR signaling (otherwise the clinical presentation would be more severe), several in-vivo studies of parasite infection in Itk −/− mice indicate a role for ITK in Th2 response." (PMID 25339095, 2014).
peripheral T-cell lymphomas (2 papers, 2017 to 2023). "ITK-SYK, which results from the fusion between SYK and ITK (IL-2-inducible T-cell kinase), occurs as a recurrent translocation in 17% of patients with unspecified peripheral T-cell lymphomas." (PMID 28881711, 2017). "Alike known oncogenic fusion ITK (interleukin-2-induced T-cell kinase)-spleen tyrosine kinase in peripheral T-cell lymphomas, ITK–FER has also been identified as another potential oncogene in peripheral T-cell lymphomas by paired DNA and RNA next-generation sequencing analysis (ITK–FER fusion 1)." (PMID 37196766, 2023).
T-cell leukemia (2 papers, 2019 to 2022). A malignant disease of the T-lymphocytes in the bone marrow, thymus, and/or blood. "Meanwhile, ASK120067 also exhibited potently anti-ITK activity in T-cell leukemia." (PMID 36588692, 2022).
allergic rhinitis (1 paper, 2019). Inflammation of the nasal mucous membranes caused by an IgE-mediated response to external allergens. "Interleukin-2-inducible T-cell kinase (ITK) is highly expressed in T-cells and has been implicated in a T-cell allergic rhinitis sub-type." (PMID 31690037, 2019).
aplastic anaemia (1 paper, 2020). "Since it is already known that ITK is engaged in the activation of T-bet, and since they found that patients with this disease showed high levels of T-bet, they suggested that there could be a connection between T-bet and ITK in the inflammatory responses of aplastic anaemia." (PMID 32808093, 2020).
Arthritis (1 paper, 2017). Inflammation of a joint. "The first irreversible BTK kinase inhibitor PCI-32765, which has demonstrated the proof-of-concept for the anti-arthritis efficacy by direct inhibition of BTK kinase, also bears potent activities against BLK, BMX, EGFR, Her2, ITK, JAK3, TEC and others." (PMID 28352114, 2017).
atherosclerosis (1 paper, 2025). A disease characterized by the build-up of fatty material and calcium deposition in the arterial wall resulting in partial or complete occlusion of the arterial lumen. "For ITK, it is necessary to clarify its role in T cell-mediated cardiovascular inflammation (e.g., atherosclerosis) and to explore the balance between its immunomodulatory effects and cardiovascular safety." (PMID 41567642, 2025). "Thus, inhibition of ITK may indirectly influence the progression of cardiovascular diseases, such as atherosclerosis, through systemic immunosuppression and modulation of the inflammatory cytokine network." (PMID 41567642, 2025).
atrial fibrillation (1 paper, 2023). A disorder characterized by an electrocardiographic finding of a supraventricular arrhythmia characterized by the replacement of consistent P waves by rapid oscillations or fibrillatory waves that vary in size, shape and timing and are accompanied by an irregular ventricular response. "Besides this on-target effect, ibrutinib deactivates several off-targets, e.g., EGFR, ErbB2, ITK, and TEC, which might contribute to the antitumor effect but, at the same time, result in adverse events, such as atrial fibrillation (AF) and bleeding." (PMID 37373521, 2023).
bladder cancer (1 paper, 2023). "Five of the 26 SMGs had not been reported as SMGs in bladder cancer in previous studies: CDKN1B (1.2%), ITK (1.8%), PRDM2 (3.1%), FOXA1 (2.7%), and BAP1 (1.8%)." (PMID 36495164, 2023).
Burkitt lymphoma (1 paper, 2023). A rare form of malignant mature B-cell non-Hodgkin lymphoma. "We cocultured Raji cells (a human EBV-positive Burkitt's lymphoma cell line) and sorted Vδ1+ γδ T, Vδ2+ γδ T, MAIT, and iNKT lymphocytes from healthy donors with or without pharmacological ITK inhibition and BiTE-triggered synapse formation." (PMID 36326697, 2023).
depression (1 paper, 2023). "ITK inhibition caused the restoration of Nrf2 signaling in the cerebral cortex, which could lead to an amelioration of a depression-like state." (PMID 37175808, 2023).
Epstein-Barr virus infection (1 paper, 2024). An infection that is caused by Epstein-Barr virus. "Cytoplasmic tyrosine kinases BTK and ITK are essential for forming B and T cells, and loss-of-function mutations in either result in X-linked agammaglobulinemia and an increased risk of a severe, usually fatal Epstein-Barr virus infection, respectively." (PMID 38166628, 2024).
gastric cancer (1 paper, 2025). A primary or metastatic malignant neoplasm involving the stomach. "Among the 19 uniquely identified genes, 7 (GSPT1, TFF3, KLF4, ITK, GNB2L1, FLI1, and GNG5) were not included in the KEGG gastric cancer pathway, indicating that they have not been previously recognized as canonical GAC-related genes." (PMID 41284725, 2025).
graft versus host disease (1 paper, 2020). An immune system disorder that occurs after allogeneic hematopoietic stem cell transplant and is a reaction of donor immune cells against host tissues. "Using pathway enrichment analyses, our data also revealed a critical role for ITK in regulating genes involved in T cell cytokine/cytokine receptor interaction, cell adhesion, graft-versus-host disease, allograft rejection, and chemokine signaling pathways." (PMID 33324410, 2020).
Granuloma (1 paper, 2019). A compact, organized collection of mature mononuclear phagocytes, which may be but is not necessarily accompanied by accessory features such as necrosis. "Among the enrichment score-driving critical genes of the TCR signaling, the levels of transcripts for ITK and its signaling components such as LCK, GRB2, SLP76, NCK1, FYN, and PLCG are significantly upregulated in caseated granulomas compared to uninvolved lung tissue." (PMID 32038633, 2019).
HIV-1 infection (1 paper, 2018). The type species of lentivirus and the etiologic agent of acquired immunodeficiency syndrome (AIDS). "The presence of lymphocyte function-associated antigen 1 (LFA-1) can increase HIV-1 infection by improving viral attachment, and ITK was shown to be involved in regulation of integrins such as LFA-120,35." (PMID 29453458, 2018). "However, other studies found that after HIV-1 infection ITK deficiency induces a late stage block of replication including virion assembly and release." (PMID 29453458, 2018). "We also tested the ITK inhibitor BIX0252428 on HIV-1 infection using the luciferase reporter viruses." (PMID 29453458, 2018). "Together, these results support the notion that ITK regulates multiple steps, early and late, during the HIV-1 infection." (PMID 29453458, 2018). "Our data indicated that ITK knockdown cells have a very early block to HIV-1 infection due to processes affecting viral binding and membrane fusion." (PMID 29453458, 2018). "Altogether, our results support the premise that ITK is an important protein that modulates the permissivity of Jurkat T-cells for HIV-1 infection that involves an unknown mechanism for HIV-1 attachment." (PMID 29453458, 2018). "Because HIV-1 infection requires proper T-cell activation, the need for ITK as a host factor likely is related to its role in integrating signaling pathways downstream of the T-cell receptor and chemokine receptors and regulation of processes important for T-cell activation and differentiation." (PMID 29453458, 2018). "The exact role of ITK during HIV-1 infection is still unknown." (PMID 29453458, 2018). "Because proper T-cell activation is required for HIV-1 infection, a function for ITK as a host factor for HIV-1 replication was expected, and recent studies confirmed a block of HIV-1 at various steps of the viral life cycle after ITK inhibition." (PMID 29453458, 2018). "ITK is not expressed in HEK293T or HeLa cells; however, if these cells are genetically modified to express CD4 and CXCR4, they are fully permissive for HIV-1 infection (data not shown)." (PMID 29453458, 2018).
hypersensitivity pneumonitis (1 paper, 2022). Hypersensitivity pneumonitis (HP) is a pulmonary disease with symptoms of dyspnea and cough resulting from the inhalation of an antigen to which the subject has been previously sensitized. "However, we show here that lung inflammation induced by Saccharopolyspora rectivirgula (SR) induced Hypersensitivity pneumonitis (SR-HP) results in a neutrophil independent, and ITK independent Th17 responses, although ITK signals are required for γδ T cell production of IL17A." (PMID 35210549, 2022).
lysinuric protein intolerance (1 paper, 2021). Lysinuric protein intolerance (LPI) is a very rare inherited multisystem condition caused by disturbance in amino acid metabolism. "HLH has also been associated with other Mendelian disorders affecting inflammation, including lysinuric protein intolerance caused by SLC7A7 defects, and CD27 and ITK deficiency caused by autosomal recessive changes in CD27 and ITK, respectively." (PMID 34677667, 2021).
myositis (1 paper, 2024). "Next, we colocalized IIM signals that overlapped IMD signals, and found seven potentially novel myositis associations mapped to immune-related genes, including BLK, IRF5/TNPO3, and ITK/HAVCR2, implicating a role for both B and T cells in IIM." (PMID 39044428, 2024).
oral cancers (1 paper, 2021). "Because ITK is a tyrosine kinase, we used mass spectrometry to investigate its tyrosine phosphorylation profile to identify novel biological behaviors in newly established oral cancer cell lines expressing ITK." (PMID 34283052, 2021). "We investigated the direct association between ITK and GART, as GART is endogenously expressed in oral cancer cell lines and HEK 293 cells." (PMID 34283052, 2021). "Oral cancer cell lines overexpressing ITK exhibited significantly increased proliferation in three-dimensional culture assays and murine inoculation models as compared with mock control cells." (PMID 34283052, 2021). "It was suggested that increases in PRPP and IMP in ITK-expressing oral cancer cells are due to the accelerated tyrosine phosphorylation of GART by ITK and activation of the de novo purine biosynthesis pathway." (PMID 34283052, 2021). "In this study, significant increases (51- to 121-fold) in levels of tyrosine phosphorylation of GART were observed in ITK-expressing oral cancer cell lines." (PMID 34283052, 2021). "We conclusively demonstrated that compared to mock control cells, de novo purine biosynthesis was enhanced in the newly generated oral cancer cell lines that express ITK." (PMID 34283052, 2021). "The resistance of oral cancers to anti-EGFR therapies could therefore be related to the overexpression of ITK, as indicated in the previous study of NSCLC." (PMID 34283052, 2021). "Consequently, we engineered SAS and KOSC2 oral cancer cells that stably express ITK and investigated the effect of ITK expression on cell proliferation in three-dimensional (3D) cultures." (PMID 34283052, 2021). "In this study, we focused on ITK as a novel molecular target in TSCC, which is the most frequent oral cancer." (PMID 34283052, 2021). "In this experiment, ITK protein expression was confirmed in clinical samples but not in oral cancer cell lines." (PMID 34283052, 2021). "To elucidate the biological role of ITK in the malignant phenotype of TSCC, we generated new lines of ITK-expressing oral cancer cells because we could not detect significant ITK expression in existing oral cancer cell lines." (PMID 34283052, 2021). "In clinical samples, ITK expression was confirmed due to the influence of the tumor microenvironment and stimulation, but it is possible that internal ITK expression could not be confirmed in oral cancer cell lines because the in vivo environment could not be reproduced." (PMID 34283052, 2021).
otitis media (1 paper, 2021). Inflammation of the anatomical structures of the middle ear, which is most often caused by an infectious process. "Furthermore, a report concerning early diagnosis of PI3Kδ syndrome in a 2-year-old girl revealed an association between ITK deficiency and recurrent otitis media." (PMID 34912812, 2021).
pulmonary aspergillosis (1 paper, 2024). "Treatment of WT mice with the BTKi ibrutinib or acalabrutinib — a second-generation BTKi that features greater selectivity for BTK and lacks ITK or TEC targeting — phenocopied the increased susceptibility to pulmonary aspergillosis observed in Btk–/– mice." (PMID 38696257, 2024).
smooth muscle tumours (1 paper, 2023). "Multiple Epstein-Barr virus–associated smooth muscle tumours with ITK mutation have rarely been reported." (PMID 37465420, 2023).
tongue squamous cell carcinoma (1 paper, 2021). A squamous cell carcinoma that arises from the tongue. "In this study, we report a possible therapeutic strategy involving the purine synthesis pathway regulated by ITK in tongue squamous cell carcinoma." (PMID 34283052, 2021). "We identified overexpression of interleukin-2–inducible T-cell kinase (ITK) as a novel biomarker for predicting the prognosis of tongue squamous cell carcinoma patients with poor outcomes." (PMID 34283052, 2021).
ulcerative colitis (1 paper, 2023). An inflammatory bowel disease involving the mucosal surface of the large intestine and rectum. "Selective targeting ITK has become an attractive method for the treatment of chronic intestinal inflammation and ulcerative colitis via driving the regression of mucosal inflammation." (PMID 36802116, 2023).
uveitis (1 paper, 2025). An inflammatory process affecting a part of or the entire uvea. "BTK inhibitors may cause uveitis through off-target immune modulation because BTK is expressed in myeloid cells and microglia; ibrutinib also inhibits ITK (important in T-cells) which could tilt immune responses and provoke ocular inflammation in susceptible individuals." (PMID 41568391, 2025).
WHIM syndrome (1 paper, 2023). "HPV‐related papilloma cancer is seen in WHIM syndrome or EVER1, EVER2, MST1, RHOH, MAGT1, ITK deficiencies." (PMID 37102642, 2023).